IL4 (interleukin 4)
Diseases named in the same sentence as IL4 in open-access papers (continued):
Sharing a sentence is not in itself a finding about the gene and the disease.
acute myeloid leukemia (14 papers, 2014 to 2025). Acute myeloid leukemia (AML) is a group of neoplasms arising from precursor cells committed to the myeloid cell-line differentiation. "These events have been linked to increased IL17 and reduced IL4 expression in CD4+ T cells in Azacytidine-treated acute myeloid leukemia (AML) and myeloid dysplastic syndrome (MDS) patients." (PMID 33859645, 2021). "Furthermore, IL-4 triggers apoptosis in acute myeloid leukemia cells through a Stat6-dependent pathway." (PMID 40362656, 2025). "When comparing newly diagnosed patients with acute myeloid leukemia (AML) and acute lymphoblastic leukemia (ALL), AML showed a significant increase in IL-4, IL-2 and IL-3, and a significant decrease in VEGF and VCAM-1." (PMID 40427092, 2025). "They act via PPARγ to reduce the severity of acute myeloid leukemia (AML) in mouse models and patient cells, suggesting IL-4 as a potential additional therapeutic option for AML." (PMID 35954274, 2022). "However, the CD34+ human acute myeloid leukaemia cell line (MUTZ-3) responds positively to granulocyte–macrophage colony-stimulating factor (GM-CSF), interleukin 4 (IL-4), and TNF-α." (PMID 41155977, 2025). "Moreover, an increase in IL-4 derived from bone marrow endothelial cells and its subsequent inhibition of bone marrow CFU-MK formation and MK maturation have been observed in mice with acute myeloid leukemia." (PMID 38256942, 2024). "In our previous clinical trials with conventional IL-4 DC vaccines [NCT01686334 and NCT00834002 for acute myeloid leukemia (AML)] we have observed favorable objective responses." (PMID 35250967, 2022).
brucellosis (14 papers, 2013 to 2026). Brucellosis is a bacterial infection that spreads from animals to people via unpasteurized dairy products or by exposure to contaminated animal products or infected animals. "During the first week of the acute phase, significant amounts of INF-γ and low levels of IL-4 are produced in B. abortus infected mice, an event that has been linked to a predominant Th1 immune response during brucellosis." (PMID 23458832, 2013). "In patients with brucellosis, the level of IL‐4 increases independently of the duration and severity of the disease, which indicates the role of this cytokine of immune system in this infectious disease." (PMID 32100374, 2020). "Evaluation of cytokines such as interleukin‐4 (IL‐4) can be an important tool in examining immune responses to brucellosis." (PMID 32100374, 2020). "According to the results, the serum levels of IL‐4 in men and women with brucellosis were 1.32 ± 0.27 pg/mL and 1.55 ± 0.72 pg/mL, respectively." (PMID 32100374, 2020). "In our univariate analysis, IL-4, IL-6, IL-10, IL-17, IFN-γ, and TNF-α were risk factors for brucellosis." (PMID 32381058, 2020). "The aim of this study was to compare the serum level of IL‐4 in patients with brucellosis and healthy controls." (PMID 32100374, 2020). "The negligible amount of IL-4 in the sera and spleen cells of infected mice during brucellosis is a well-known feature and delineates the Th1 predominant immune response." (PMID 30804100, 2019). "A Th2 response, driven by IL-4 and IL-10, is detrimental to combating brucellosis as it promotes humoral immunity and suppresses macrophage activation." (PMID 24040434, 2013). "Notably, the chronic form of bovine brucellosis was associated with increased expression of IFN-γ, IL-1β, IL-6 and iNOS genes, along with reduced expression of TNF-α, IL-4 and IL-12p40 genes." (PMID 39825331, 2025). "• Conferring a significant level of protection in animals due to inducting a specific Th1 response (antibody), increased IFN-γ expression level compared with IL-4, and a strong T cell-proliferative response• BvrR is a promising candidate for studies on DNA vaccines against brucellosis in the future." (PMID 35923818, 2022). "In this study, we examined the relationship between brucellosis and cytokine levels, and found IL-4, IL-6, IL-10, IL-17, IFN-γ, and TNF-α were all risk factors for brucellosis, although only IL-6 and INF-γ were independent risk factors for the severity of brucellosis." (PMID 32381058, 2020). "Levels of IL-4, IL-6, IL-10, IL-17, IFN-γ, and TNF-α were all significantly higher in those with brucellosis than in the control group (all P < 0.05)." (PMID 32381058, 2020). "We investigated changes in the levels of six cytokines (IL-4, IL-6, IL-10, IL-17, TNF-α, INF-γ) and related clinical biochemical markers in patients with acute and chronic brucellosis in Xinjiang, China." (PMID 32381058, 2020). "To investigate changes in CD4+ and CD8+ T cell subsets in patients with acute brucellosis, we analyzed the following subsets in the blood: CD4 + IFN-γ + (Th1), CD4 + IL-4+ (Th2), CD8 + IFN-γ + (Tc1), and CD8 + IL-4+ (Tc2)." (PMID 32660627, 2020). "We found that IL-4, IL-6, IL-10, IL-17, IFN-γ, and TNF-α levels were higher in patients with brucellosis than healthy controls, indicating a strong immune response was occurring." (PMID 32381058, 2020). "We found that IL-4, IL-6, IL-10, IL-17, IFN-γ, and TNF-α levels were higher in those with brucellosis than in controls (P < 0.05)." (PMID 32381058, 2020). "We found that IL-4, IL-6, IL-10, IL-17, IFN-γ, and TNF-α levels were higher in those with brucellosis than in controls." (PMID 32381058, 2020). "We have observed unmodified levels of specific IL-4 production among all group of mice, which indicated no involvement of this Th2 representative cytokine in the immune response against brucellosis." (PMID 34078437, 2021).
brucellosis (continued). "IL-4 is the main cytokine released by Th2 cells to exert humoral immunity, which is not conducive to curing brucellosis." (PMID 32381058, 2020). "In agreement with the Th1 predominant immune response during brucellosis, practically no IL-4 or IL-17 cytokines were measurable during Brucella infection in either mouse group." (PMID 23458832, 2013). "Though gene expression of the Th2 cytokine IL-10 was elevated in some brucellosis patients, IL-10 protein secretion was not significantly altered in these patients under any stimulation condition; IL-4, another important Th2 cytokine, was not highly secreted in any condition." (PMID 24040434, 2013). "Moreover, the significant induction of CD4+IFN-ɣ+ T-cells after S19 or RB51 vaccination and RB51 revaccination (RB51 group), as well as the absence of an IL-4 response, characterize the development of a predominant Th1 immune response following brucellosis vaccination in cattle." (PMID 26352261, 2015).
Chagas disease (14 papers, 2013 to 2025). A parasitic infection caused by Trypanosoma cruzi. "So far, most studies addressing the function of IL-4Rα-mediated signaling in experimental Chagas disease employed IL-4-deficient(−/−) and STAT6−/− mice or neutralization of IL-4 by administration of monoclonal antibodies." (PMID 30555475, 2018). "Higher levels of IFNγ and TNFα are associated with lower levels of IL-4 and IL-10, in both cardiac and more severe forms of Chagas disease, and high levels of IL-10 or moderate levels of IFNγ are associated with the indeterminate form." (PMID 24216069, 2013). "In Chagas disease, the 2590T allele (rs2243250) polymorphism in the promoter region of IL4 gene is a marker for IL4 haplotypes likely associated with protection against T. cruzi infection." (PMID 24069594, 2013). "The poor expression of IL-4 and IL-13 after experimental infection of wildtype mice with T. cruzi nearly exclude a reasonable analysis of the contribution of the IL-4Rα-Arg-1 pathway in susceptibility to experimental Chagas disease." (PMID 30555475, 2018). "Inflammatory cardiac infiltrate in Balb/c WT and Balb/c IL-4−/− mice infected with Colombian strain in acute phase of experimental Chagas disease was analyzed." (PMID 30622430, 2018). "The present study was designed to determine whether SNPs in IL12B, IL10, IFNG and IL4, key genes involved in the promotion and control of Th1 differentiation and IFN-g production to T. cruzi, are associated with Chagas disease outcome." (PMID 32733459, 2020). "In contrast to TNF-dependent modulations, our own data point to IL-4 as a soluble factor in T. cruzi-infected mice that may contribute to stromal cell alterations during the acute phase of Chagas disease." (PMID 30619242, 2018). "However, IL-4 activity was abolished when the synthesis of endogenous galectin-3 was interrupted, clearly demonstrating the existence of a mechanism of cross-talk between IL-4 and galectin-3 in the context of acute Chagas disease." (PMID 35046919, 2021). "P21 also has the capacity to induce an immune response through IL-4, IL-10, and IFN-γ production in T. cruzi infection, contributing to the control of parasite proliferation in the host organism and at the same time triggering the pathogenesis of Chagas disease." (PMID 37915581, 2023). "In our cohort of chronically infected Chagas disease patients, those with detectable T. cruzi parasitemia measured through RT-PCR in peripheral blood had a higher concentration of pro-inflammatory cytokines (TNF-α, IL-1β, IL-6 and IL-17A) and IL-4 than those with negative RT-PCR." (PMID 38133693, 2023).
conjunctivitis (14 papers, 2020 to 2026). Inflammation of the conjunctiva of the eye. "The cause of dupilumab-associated conjunctivitis, as well as the relationship between its various pathogenetic mechanisms, are currently unclear, but possible hypotheses include inhibition of IL-4 and IL-13 signaling pathways involved in the development of atopic keratoconjunctivitis." (PMID 32599878, 2020). "This pattern suggests a potential contribution of IL-4 blockade to conjunctivitis development, although further studies are warranted to delineate the specific roles of IL-4 and IL-13 in conjunctival homeostasis." (PMID 40725651, 2025). "Other authors have confirmed that sparing IL-4 in the selective blockade of interleukin-13 in patients treated with tralokinumab leads to a smaller Th2/Th1 immune switch and a lower incidence of conjunctivitis compared to those treated with dupilumab." (PMID 38999383, 2024). "Meanwhile, conjunctivitis was linked to elevated levels of IFN-γ (p = 0.0306), IL-4 (p = 0.0112), and CXCL10 (p = 0.0332)." (PMID 37235332, 2023). "Although it appears that blocking IL-4 and IL-13 can trigger eye disorders, including conjunctivitis, there are still factors to consider about dupilumab-related eye disorders." (PMID 34253801, 2021). "Likewise, conjunctivitis found in our cohort was linked to significant increases in CXCL10 (p = 0.0332), followed by IL-4 (p = 0.0112) and IFN-γ (p = 0.0306) levels." (PMID 37235332, 2023). "It is worth exploratory whether conjunctivitis results from the blockade of IL-4 and IL-13 with dupilumab or that conjunctivitis, in the first place, is part of this systemic allergic disorder." (PMID 35308529, 2022). "Because early trial data indicate that tralokinumab may be less likely to drive AOEs compared with dupilumab, for the same indications, a careful examination of real-world evidence will be necessary to establish this and whether IL-4, IL-13, or both are the drivers for the conjunctivitis observed." (PMID 36525340, 2023). "Lastly, regarding differentiating OX40-OX40L inhibitors from existing AD biologics in terms of safety profiles, the OX40-OX40L inhibitors do not have the adverse effect of conjunctivitis, which is related to the use of IL-4 and/or IL-13 inhibitors." (PMID 38607026, 2024). "Dupilumab (an IL-4 and IL-13 pathway inhibitor) has not been studied in AC, but one reported adverse effect of the drug is conjunctivitis, described as inflammation of the anterior conjunctiva and hyperemia of the limbus." (PMID 31993069, 2020).
glaucoma (14 papers, 2012 to 2024). Increased pressure in the eyeball due to obstruction of the outflow of aqueous humor. "The anti-inflammatory cytokines IL-4 and IL-10 may play a compensatory role early in glaucoma, prior to functional transport loss and RGC death, and could induce alternative activation and polarization of M2 microglia." (PMID 33669765, 2021). "In a previous study, patients with glaucoma showed higher serum levels of IL-4 and IL-6 and those with severe optic neuropathy showed even higher levels, also suggesting the role of abnormal immune environment in the glaucoma pathogenesis." (PMID 38724620, 2024). "In a glaucoma mouse model, increased expressions of inflammatory cytokines, including interferon-γ, IL-6, IL-4, IL-10, and IL-1β were found." (PMID 37744880, 2023). "In tear samples, an increase in IL-4, IL-12, IL-15, IL-6, and IL-8 in patients with glaucoma have been reported." (PMID 34575451, 2021). "For example, one previous study found that serum interleukin (IL)-4 and IL-6 cytokines produced by T helper cell 2 were elevated in glaucoma patients; these cytokines also activate B cells to produce IgE." (PMID 29285264, 2017). "Notably, the aqueous humor of patients with glaucoma has higher concentrations of cytokines, such as IL-4, IL-6, IL-8, IL-10, vascular endothelial growth factor, and interferon-α, compared to healthy individuals." (PMID 38651060, 2024). "Levels of IL-2 or IL-4 in glaucoma patients are controversial in previous studies." (PMID 37020269, 2023). "Therefore, we simultaneously compared serum and aqueous levels of TNF-α, IL-2, TGF-β2 and IL-4 and investigated the possible effects of cytokine levels on clinical characteristics and postoperative outcomes in glaucoma patients." (PMID 37020269, 2023). "Additionally, IL-6 was higher in the ‘POH group’ compared to the ‘glaucoma group’ (p = .04) and IL-4 was higher in the ‘POH group’ compared to the ‘normal group’ (p = .04)." (PMID 35998207, 2022). "Consequently, IL-4 emerges as a promising molecular target for therapeutic interventions aimed at mitigating disorders associated with RGC degeneration, such as traumatic optic neuropathy and glaucoma." (PMID 38650003, 2024). "Additionally, when evaluating AH from human patients with glaucoma, IL-4 has been undetectable." (PMID 35998207, 2022). "IL-4 and IL-6 levels were higher in the ‘POH group’ compared to the ‘normal group‘ and ‘glaucoma group’, respectively." (PMID 35998207, 2022). "Our previous clinical study showed significantly lower serum TNF-α in primary open-angle glaucoma (POAG) patients than in controls, while the levels of IL-4, IL-6, and IL-12p70 were significantly higher." (PMID 25811482, 2015). "Significantly higher serum levels of IL-4, IL-6, and IL-12 (p70), along with lower TNF-α, were determined in POAG patients compared to controls, suggesting abnormal immune environments contributing to glaucoma." (PMID 34439995, 2021). "IL-4, IL-5, CCL3, and G-CSF was detected in less than 50% of samples in both control and glaucoma groups and therefore were not included in further analysis." (PMID 22355254, 2012).
inflammatory skin disease (14 papers, 2013 to 2025). Inflammatory skin disorders covers a broad category that includes many conditions ranging in severity, from mild itching to grave medical health complications These disorders are common in people of all ages and races. "ACD is an inflammatory skin disease, driven by a complicated cell-cell network mediated by several T cell-associated cytokines, including Th1 cytokine IFNγ, Th2 cytokines IL4, IL13, and Th17 cytokine IL17." (PMID 39213029, 2024). "In ACD and other related skin inflammatory disorders, IL-4 and IL-17 are the key cytokines responsible for their pathophysiology." (PMID 40943049, 2025). "The inflammatory skin disease is characterized by cutaneous hyperreactivity to allergens and by a microenvironment in the skin enriched with Th2 cytokines, such as IL-4 and IL-13, and histamine released from activated immune cells." (PMID 34769080, 2021). "T helper 2 (Th2)-mediated dermatoses are inflammatory skin diseases driven by CD4+ Th2 cells that produce interleukin (IL)-4, IL-5, IL-13, and IL-31, promoting immunoglobulin E (IgE) class switching, eosinophil recruitment, mast cell degranulation, and pruritus." (PMID 41226755, 2025). "Exotoxins secreted by S. aureus take part in mechanisms of escape from the immune system to ensure survival and spreading within tissues and the δ-toxin secreted by S. aureus has been shown to promote IgE and IL-4 production as well as inflammatory skin disease in a mouse model." (PMID 26510097, 2015). "In patients with inflammatory skin disorders, these TH22 cells were found to produce only IL-22 but not IFNγ, IL-4, or IL-17." (PMID 23460846, 2013).
leptospirosis (14 papers, 2012 to 2025). A contagious bacterial infection caused by spirochetes of the genus Leptospira. "Serum levels of IL-4 were increased in human patients and frequencies in IL-4 and IL-4R receptor gene polymorphisms were significantly higher in leptospirosis patients compared to healthy subjects." (PMID 36551258, 2022). "Patients with a history of leptospirosis exhibited considerably more polymorphisms in the IL-4 and IL-4R genes." (PMID 36551258, 2022). "Serum levels of IL-4 were also increased in human patients and frequencies in IL-4 and IL-4R receptor gene polymorphisms were significantly higher in leptospirosis patients compared to healthy subjects." (PMID 29974037, 2018). "For example, in canine leptospirosis, interleukin-4 is a key component of the complex immune response, potentially contributing to the development of the disease and its severity." (PMID 40732660, 2025). "A previous systematic review showed elevated levels of cytokines (IL-1β, IL-2, IL-4, IL-6, IL-8, IL-10, TNFα) in severe human leptospirosis compared with mild leptospirosis." (PMID 39729468, 2024). "Especially, TNF-α and the interleukins IL-1β, IL-2, IL-4, IL-6, IL-8, and IL-10 were elevated in severe leptospirosis cases, whereas TNF-α, IL-6, IL-8, IL-10, interferon-γ, and soluble TNF receptor 1 were elevated in high fatality cases." (PMID 35237527, 2021). "Control and leptospirosis groups had similar distribution of IL-4 in both white and red pulps and this expression was higher than that of the septic group in the red pulp." (PMID 31114579, 2019). "IL-4 is induced during leptospirosis with late but massive overexpression in blood from experimentally infected hamsters." (PMID 29974037, 2018). "It has also been suggested that, among other factors, polymorphisms in IL-4 and IL-4R and IL-1β, IL-12R, and CISH (multiple cytokines inducible SH2-containing protein gene) correlated with susceptibility to leptospirosis." (PMID 28270811, 2017). "IL-4, IL-6, IL-8, IL-10, IL-17A, and TNF-α levels in severe leptospirosis compared to mild disease, and an association between high IL-6, IL-8, IL-10 and fatal outcome." (PMID 26824356, 2016). "Thus, induction of IL-4 and IL-10 might play an important role in leptospirosis pathophysiology that still needs to be precisely described." (PMID 29974037, 2018). "Several earlier studies have identified significant expression of IL-1β, IL-2, IL-4, IL-6, IL-8, IL-10 and TNF-α in severe leptospirosis." (PMID 35584087, 2022). "Significantly higher concentrations of IL-1β, IL-2, IL-4, IL-6, IL-8, IL-10, IL-17A, and TNF-α were found in sera of leptospirosis patients." (PMID 35927283, 2022). "IL-1b, IL-2, IL-4, IL-6, IL-8, IL-10 and TNF-α levels were found to be significantly higher in severe than in mild leptospirosis." (PMID 32264832, 2020). "The cytokine profile revealed that the levels of at least sixteen cytokines were significantly elevated in the leptospirosis patients’ sera, including the major proinflammatory factors IL-1β, IL-6 and TNF-α, and the major anti-inflammatory factors IL-4, IL-10 and IL-13." (PMID 22870312, 2012). "The role of IL-4 has been studied in mice, but the resistance of BALB/c/IL-4ko mice to the infection with L. interrogans serovar Copenhageni strain Fiocruz L1-130 was comparable to WT BALB/c, suggesting that IL4 does not play a major role in leptospirosis in these mice." (PMID 28270811, 2017).